STAT3 (signal transducer and activator of transcription 3)
Diseases named in the same sentence as STAT3 in open-access papers (continued):
Sharing a sentence is not in itself a finding about the gene and the disease.
tumor (continued). "Moreover, ponatinib showed anti-tumor efficacy in an orthotopic xenograft NB mouse model by blocking the activity of PI3K/AKT/mTOR and JAK/STAT3 signaling pathways." (PMID 27564113, 2017). "Indeed, in MM patients, tumor-released suppressive factors (such as TGF-β, IL-10, IL-6 and VEGF) can abrogate DC function, by activation of STAT3." (PMID 28435516, 2017). "In addition, we further analyzed the tumor vasculature by combining FVIII and Stat3 dual immunofluorescence reactions and fluorescence in situ hybridization using the Stat3 locus specific probe (Chr:17q21.2) and the probe for chromosome 9q34.11." (PMID 28415725, 2017). "More importantly, co-expression of Stat3 in these cells restored the number of lung tumors to that seen in control conditions, revealing how the inhibitory action of RIP4 on STAT3 signaling impacts tumor cell invasiveness." (PMID 28574510, 2017). "We suggest that the abnormal signaling and expression of c‐kit/SCF, c‐myc, and STAT3 in NK cells is responsible for the defect in their cytolytic activity in cancer and these defects at the gene expression level may be the cause rather than the result of tumor progression." (PMID 28695716, 2017). "SOCS3 expression moderately detected in vivo in BCC and SCC lesions can be influenced by the complex tumor microenvironment, where other cytokines, such as IL-6, could induce SOCS3 via STAT3." (PMID 28445952, 2017). "Further, LY5 anti-proliferative activity was similar in control cells and cells where STAT3 had been depleted, indicating that the anti-tumor effects of LY5 are not due to STAT3 inhibition." (PMID 28750090, 2017). "On the other hand, it shows anti-tumor activity through the activation of lymphocytes including cytotoxic T (CD8+) and natural killer (NK) cells, and inactivation of the nuclear factor-κB (NF-κB) and STAT3 signaling pathways." (PMID 29050245, 2017). "On the other hand, in the protein expression profile of SSC-2, the neoplastic proliferation of tumor cells was related to the overexpression of PCNA, MPM2, KRAS, STAT3, EGFR, and bFGF and was supported by the overexpression of the protein translation factors eIF5A, DHS, and DOHH compared to SSC-1." (PMID 28789700, 2017). "The results suggest that FGFR1-activated PI3K/AKT/mTOR and JAK/STAT3 signaling pathways may promote NB development and ponatinib-induced inhibition of FGFR1 signaling contributes to its anti-tumor effects." (PMID 27564113, 2017). "Moreover, NANOG was reported to be upregulated by a number of factors such as STAT3, Hedgehog signaling, hypoxia, etc., in human cancers, and repression or ablation of NANOG inhibited tumor initiation." (PMID 28116670, 2017). "However, genetic inhibition of IKK-β long after tumor initiation accelerated HCC development and enhanced proliferation of tumor initiating cells, mainly by ROS accumulation and c-Jun N-terminal kinase (JNK) and STAT3 activation." (PMID 27888618, 2017). "All patients with SMAD7 T/N ratios <1 showed strong pSMAD2 positivity in the tumors, suggesting enhanced TGF-β signaling in tumors with low SMAD7 levels, while STAT3 signaling was only activated in three patients and not all tumor cells." (PMID 28134936, 2017). "Furthermore, the cytotoxicity of spleen lymphocytes against H22 cells was stronger in the presence of serum from mice immunized with the STAT3-blocked HCC vaccine, suggesting that tumor-specific IgG was essential for inhibiting tumor growth." (PMID 29115974, 2017). "Furthermore, REP1 knockdown effectively reduced tumor growth in a mouse xenograft model via EGFR downregulation and STAT3 inactivation in vivo." (PMID 28230863, 2017). "In the current study, we found that the expression of STAT3 was higher in lymph node lesions than that in ICC primary tumor tissues in most cases, which suggested that high STAT3 expression correlated with a greater likelihood of lymph node metastasis." (PMID 28032598, 2017).
tumor (continued). "Supporting this discovery, Tang and colleagues showed that ovarian CSCs can activate NFκB and STAT3 signaling secreting CCL5 and activating this pathway in an autocrine manner to allow its own differentiation into endothelial cells to improve tumor angiogenesis." (PMID 28819364, 2017). "In contrast to in vitro data suggesting an inverse relationship between HBx–NF-κB–SHP2 activity and STAT3 signaling, HCC-surrounding non-neoplastic tissues exhibited increased IL-6–JAK–STAT3 signaling compared with matched tumor tissues." (PMID 28460481, 2017). "Finally, according to the results obtained in tumor cells, DHA-induced STAT3 de-phosphorylation was reduced by OV, suggesting a role for tyrosine phosphatases in DHA-mediated STAT3 de-phosphorylation in immune cells." (PMID 28435516, 2017). "Additionally, GLI1, p-STAT3, STAT3, and SOCS3 were detected both in the tumor and the adjacent stromal tissues, indicating that the involvement of these proteins in the tumor microenvironment." (PMID 27275540, 2017). "In summary, this study demonstrated that radiation led to the upregulation of PD-L1 expression in tumor through increased IFN-γ and enhancing the activity of STAT3, which could facilitate the antitumor effect of anti-PD-L1." (PMID 28465485, 2017). "All these studies illustrated that TIM-3 may promote cancer progression through IL-6/STAT3 pathway or inhibiting IFN-γ production of effective T cells against tumor cells, exhibiting the function as a tumor-promoting role." (PMID 28423646, 2017). "In particular, we demonstrate that blockade of the IL-6/STAT3 axis eliminates FGF19-induced tumour formation without compromising the metabolic functions of FGF19 in regulating bile acid, glucose and energy homoeostasis." (PMID 28508871, 2017). "Since EGFR, HER-2 and STAT3 were known as important proto-oncogenes in gastric tumourigenesis, MEG2 might be an effective tumour suppressor in GC." (PMID 28747184, 2017). "Furthermore, the alpha fetoprotein (AFP), tumor size, pathological satellite, microvascular invasion, TNM stage and STAT3 levels were statistically correlated with DFS." (PMID 28032598, 2017). "In addition, Shp2 leads to Stat3 dephosphorylation of murine keratinocytes after ultraviolet B (UVB) irradiation, implying a tumor suppressor role for Shp2 in UVB-mediated skin carcinogenesis." (PMID 28085101, 2017). "Our previous studies demonstrated that Stat3 and non-coding RNAs contribute to overexpression of Jab1/COPS5 in cancer, and highly expressed Jab1/COPS5 regulates DNA damage response, which confers chemotherapy and radiotherapy resistance to tumor cells." (PMID 29228627, 2017). "Our studies, carried out on sixty-five FFPE tissues, confirmed the constitutively activation of STAT3 protein (pY705-STAT3) in tumor samples, without any relevant variation in expression levels between the Gleason grades." (PMID 28489571, 2017). "IHC staining showed that the expression of p-STAT3 was correlated with tumor grade, but not other parameters of HNSCC." (PMID 28270740, 2017). "Like TNF-α, IL-6 facilitates tumor development by promoting the conversion of non-cancer cells into tumor stem cells in vitro via Oct4 gene upregulation expression through IL-6R/JAK/STAT3 signaling." (PMID 28030810, 2017). "As a potent STAT3 activator, IL-22 is a member of the IL-10 cytokine family, principally produced by Th22 and Th17 subsets of CD4+ T cells which play important roles in tumor development." (PMID 28445985, 2017). "Moreover, WCE significantly downregulated STAT3/S100A8 signaling, limited the expansion of MDSCs, and targeted the release of downstream chemokines from cancer cells, which prevented the tumor microenvironment entering a vicious cycle." (PMID 29142311, 2017). "This demonstrated that STAT3 signaling in the tumor cells did not affect the immune cell independent apoptotic rate of the tumor in our system." (PMID 28008146, 2017).
tumor (continued). "Moreover, continuous EGFR signaling from late endosomes was shown to contribute to sustained downstream AKT and STAT3 activation and the endosomal accumulation of the activated EGFR increased tumor cell survival." (PMID 29176966, 2017). "Moreover, FGF19 and BIRC5 were concomitantly overexpressed in all 10 of these tumour samples, further establishing a positive correlation between the expression of FGF19 and BIRC5, a STAT3 target gene, in human HCC." (PMID 28508871, 2017). "In addition, IL-6, STAT3 and HIF1 protein levels in Hep2-CSC were consistently and significantly increased as compared with that from Hep2 cells or Hep2-derived tumor tissue (p < 0.001)." (PMID 28878571, 2017). "DHA strongly suppressed both constitutive and tumor cell conditioned medium (TCCM)-induced activation of STAT3 in both PBMCs and DCs, indicating that DHA can inhibit STAT3 signaling in immune cells and has the potential to counteract STAT3 activation induced by MM cell-released factors." (PMID 28435516, 2017). "IL-6, STAT3 and HIF1 mRNA levels in Hep2-CSC were significantly increased as compared to the IL-6, STAT3 and HIF1 mRNA expression levels in Hep2 cells and Hep2-derived tumor tissue, which were obtained from the tumor tissue after Hep2-cells were injected into dorsal area of nude mice (p < 0.001)." (PMID 28878571, 2017). "All these results suggest that SOCS3 is a direct target of miR-222-3p, and exosomic miR-222-3p might enhance tumor malignancy through SOCS3 and its downstream effectors, such as the Jak2/Stat3 and Bcl-2 pathways." (PMID 28743280, 2017). "QRHX inhibited tumor cell-TAMs interactions via the suppression of cancer-related inflammation and probably blocking the response of macrophages to tumor signals, CXCL12/CXCR4/JAK2/STAT3 axis." (PMID 28630636, 2017). "Our current study further implied that Stat3 activity is important for CRC response to nifuroxazide, and Stat3 inhibition by nifuroxazide direct the proapoptotic activity on tumor cells and positive effects on tumor immunologic microenvironment." (PMID 28055016, 2017). "Ursolic acids could inhibit the migration and invasion of tumor stem cells through downregulating MMP-2 and upregulating TIMP-2, while EGCG could inhibit STAT3 signaling pathway." (PMID 28969057, 2017). "Analysis of glioblastoma tumor specimens revealed the presence of both US28 and phosphorylated Stat3, demonstrating that US28 may play role in tumor development in vivo." (PMID 28228690, 2017). "Furthermore, immunohistochemistry revealed that the expression of p-STAT3 and VEGF was suppressed and cleaved caspase 3 was activated in tumor sections isolated from PROS treated group mice compared to untreated control." (PMID 29254203, 2017). "We silenced STAT3 signaling by transducing homogenized tumor cells between the serial passages in the non-humanized mice prior to the autologous reconstitution in the humanized mice." (PMID 28008146, 2017). "Worth to note, CNAs of 37 genes were exclusively found in G3 tumours such as WNT7B (4 gains), BAD (3 gains), WEGFB (3 gains) and HDAC2 (3 losses) in respect to 65 CNA genes exclusively presented in G1 tumours, such as GRB2 (5 losses) and FGF21, STAT3, CTNNA3 and DVL3 with 3 losses each." (PMID 28486536, 2017). "Moreover, the expression of p-STAT3 and VEGF, which present the formation of vessel in tumor mass, was significantly suppressed in miR-29b-injected tumors." (PMID 28122338, 2017). "The expression of S100A9 in monocytes exerts a tumour-promoting effect upon co-culture with oral cancer cells, in particular by releasing IL-6 and the activation of NF-κB or STAT-3 that is not achieved in tumour cell monoculture." (PMID 28381274, 2017). "In summary, the present study confirmed that SFN not only affects ECs function but also the interaction between HCC cells and ECs by inhibiting STAT3/ HIF-1α /VEGF signalling in the cancer cells, which results in the suppression of angiogenesis induced by HCC cells leading to an anti-tumor effect." (PMID 28978924, 2017).
tumor (continued). "Administration of recombinant human IL11 to mice (n = 4/group) activated IL11 downstream target, signal transducers and activators of transcription (STAT3) and significantly increased tumour growth (p < 0.05), suggesting that IL11 promotes high grade tumour growth." (PMID 28186993, 2017). "Emerging STAT3-null tumours re-established immune suppression based on the absence of a robust Granzyme B+ response and impaired nuclear STAT1 translocation." (PMID 28276425, 2017). "In addition, selective inhibition of STAT3 by small molecule inhibitors suppresses CD44+/CD24−/ALDH+ BCSCs, mammosphere-forming efficiency and tumor growth in human breast tumor xenograft rodents." (PMID 28445439, 2017). "Conditioned media from HNSCC tumor cells did not induce T-cell migration, while media from same cell lines whose STAT3 gene was suppressed (“Stat3 knockout”) induced T-cell migration as much as our positive control treatment (“100% serum”)." (PMID 28008146, 2017). "An increasing number of studies have reported that STAT3 is constitutively activated in a variety of malignancies including HNSCC, and this activation is closely related to the process of carcinogenesis and tumor progression." (PMID 28270740, 2017). "Moreover, blockade of activation of STAT3 signaling results in the induction of apoptosis and cell cycle arrest in GBM cells and prolonging survival in GBM xenograft tumor models." (PMID 28054986, 2017). "Indeed, Terence and the colleagues reported that CD24+ liver tumor-initiating cells drive self-renewal and tumor initiation through STAT3-inducing NANOG expression, indicating that STAT3 signaling played important roles in the maintenance of CSCs in HCC." (PMID 28750679, 2017). "Furthermore, icaritin treatment clearly reduced the expression of p-STAT3 and p-JAK2 in the epithelium of the tumor compared with untreated control." (PMID 28085115, 2017). "STAT3 and HIF-1α increase the expression of VEGF thus promote tumor angiogenesis." (PMID 28978186, 2017). "Although the metformin treatments inhibited expression of STAT3 and its target proteins, the change in tumor weight was not significant in the 100 and 200 mg/kg metformin treatment groups." (PMID 28114390, 2017). "On the contrary, targeting STAT3 could block expression of VEGF induced by multiple oncogenic growth signaling pathways, and then inhibit tumor angiogenesis." (PMID 28764703, 2017). "Ablation of STAT3 expression through the use of conditional knockout mice or selective STAT3 inhibitor markedly reduces the expansion of MDSC and increased T cell responses in tumor-bearing mice." (PMID 29340089, 2017). "Likewise, HA-RHAMM interaction enhanced phosphorylation of EGFR, ERK1/2, and STAT3, and these effects were blocked by gefitinib, an inhibitor of EGFR signaling, suggesting that HA-RHAMM signaling uses EGFR to promote tumor cell survival." (PMID 28460475, 2017). "To verify our hypothesis that metformin inhibits tumor angiogenesis by suppressing JAK/STAT3/c-MYC signaling pathway, we detected the expression levels of related genes and proteins in tumor specimens from mice." (PMID 29088816, 2017). "Tumor tissues evaluated using IHC assay also showed that simvastatin treatment increased p21 and p27 expression, increased AMPK activation, decreased Skp2 expression and reduced STAT3 phosphorylation." (PMID 28230855, 2017). "To determine whether Cucurbitacin D inhibits the phosphorylation of STAT3 and AKT in in vivo condition, we performed IHC of pAKT and pSTAT3 in excised xenograft tumor tissues of control and Cucurbitacin D administered mice." (PMID 27824155, 2016). "To assay TKI-induced anti-tumor responses we used EGFRL858R and the EGFR downstream pathway proteins, ERK1/2 (phospho-ERK1/2 Thr 202/Tyr 204), AKT (phospho-AKT Thr 308) and a signal transducer and activator of transcription 3 (phospho-STAT3 Tyr 705)." (PMID 27494838, 2016). "Activated STAT3 contributed to cell proliferation and angiogenesis in a KSHV tumor model in mice." (PMID 27458446, 2016).
tumor (continued). "Deficit of oxygen availability within tumor microenvironment directly regulates the HIF-1α signal, however, the activation of HIF-1α is not only induced by hypoxia, but also via various kinases cascade, for example, STAT3." (PMID 27806334, 2016). "Moreover, STAT3 was regarded as the key transcription factor to the promoter of VEGF in normal and tumor cells." (PMID 27494878, 2016). "That any one of three signaling pathways can maintain expression of these proteins in the face of the drug combination argues that it is the ability of [ruxolitinib + MMF] to simultaneously inhibit the STAT3, AKT and MEK-ERK pathways which is crucial in promoting tumor cell killing." (PMID 26981780, 2016). "Furthermore, TAM-derived IL-6 induced CD44+ stemlike cell expansion by activating STAT3, and blocking IL-6 with tocilizumab ablated CD44+ sphere formation in vitro and tumor growth in patient-derived HCC xenografts." (PMID 26980947, 2016). "These properties could be attributed to STAT3-mediated transcriptional activation of cellular genes such as MUC1, c-Myc, VEGF, and cyclin D1, all known for their tumor-promoting functions." (PMID 27458446, 2016). "In summary, our results are consistent with a model that suggests that the ratio of STAT1 to STAT3 expression (without the necessity of STAT1 tyrosine phosphorylation) dictates CRC tumor growth." (PMID 27191495, 2016). "We could also show that leptin activates potent oncogenic pathways depending on JAK2/STAT3, AKT and ERK1/2 in the tumor cell line that carried a high-copy amplicon on the locus of the leptin receptor." (PMID 26871287, 2016). "We found that cZNF292 silencing decreased the transcriptional activity of E2F1, NF-κB, Sp1, HIF-1, AP-1, STAT3, and STAT5 in the U87MG and U251 cell lines, suggesting that cZNF292 silencing represses tumor tube formation through altering transcription factor activity." (PMID 27613831, 2016). "Further, supernatants from STAT3-targeted HCC cells enhanced the cytolytic activity of NK cell lines against HCC tumor targets, suggesting that the profile of secreted factors by the tumor cells was altered by STAT3 inhibition." (PMID 27148255, 2016). "In both tumor cell lines, the addition of gemcitabine to the IL-6-stimulated cells did not decrease STAT3 phosphorylation." (PMID 27687804, 2016). "Cell autonomous and non-immune effects of STAT3 deletion in tumor cells were excluded, as markers of proliferation, angiogenesis, and apoptosis were similar in tumors from WT or STAT3−/− mice." (PMID 27148255, 2016). "Furthermore, STAT3 has been reported to be involved in the regulation of VEGF expression, tumor angiogenesis and metastasis." (PMID 27210483, 2016). "The decreased Tyr 705 phosphorylation of STAT3 in gramisterol or cytokines from RBDS-treated splenocytes culture and IFN-γ treated cells resulted in transcription inhibition of the genes for growth and proliferation of the tumor cells." (PMID 26752299, 2016). "Ectopic NFIB expression activated phospho-STAT3 signalling only in classical and mesenchymal GBM cells, suggesting a mechanism through which NFIB may exert its context-dependent tumour suppressor activity." (PMID 27083054, 2016). "Moreover, the experiments on tumor-bearing mice showed that GW4064/CDDP co-treatment inhibited the tumor growth in vivo by up-regulating SHP expression and down-regulating STAT3 phosphorylation." (PMID 27127878, 2016). "Therefore, p-STAT3 expression by TILs, CRC cells, and tumor after EBI3 block were analyzed by Western blotting, FCM, and IHC, respectively." (PMID 27247488, 2016). "Exogenous STAT3 and CDDP may synergistically inhibit the xenograft tumour growth through up-regulation of BAX protein via GRP78." (PMID 27129294, 2016). "STAT3 activation results in the secretion of malignant pleural effusion proteins and VEGF upregulation in patients' samples as well as increased cell colony formation in soft agar and tumor formation in nude mice." (PMID 27445423, 2016).